BRCA2 (BRCA2 DNA repair associated)
Diseases named in the same sentence as BRCA2 in open-access papers (continued):
Sharing a sentence is not in itself a finding about the gene and the disease.
cancer (continued). "Mutations in the BRCA1 or BRCA2 genes result in a defect in HR repair, which causes cancer cells with these mutations to become “addicted” to error-prone alt-EJ pathways for their survival." (PMID 32660124, 2020). "Mutations in the tumor suppressor gene BRCA2 (BReast CAncer susceptibility gene 2) predispose carriers to breast, ovarian, and other cancers." (PMID 32638521, 2020). "One illustration of this is the sensitization of BRCA1- or BRCA2-deficient cancers to PARP inhibitors." (PMID 32660124, 2020). "Six pathogenic variants (in BRCA1,BMPR1A,FANCA,FANCC,NBN genes) with cancer related phenotype and three unsolicited variants (in BRCA2,PALB2,RAD50 genes) were reported to patients." (PMID 31937788, 2020). "Approximately 16% of women with a BRCA1 or BRCA2 mutation experience distress levels comparable to those of women after a cancer diagnosis." (PMID 32393849, 2020). "Mutation in BRCA1 or BRCA2 in HR-deficient cancer cells will lead to the repair of DSBs via error-prone repair pathways, accumulation of mutations and eventually cell death." (PMID 32316968, 2020). "In the current study, we report on frequency and predictors of cancer-related distress in a large international cohort of unaffected women with BRCA1 or BRCA2 mutations aged 25 to 55 years." (PMID 32393849, 2020). "Nevertheless, it seems that the lethal interaction only happens in specific cell lineages, specifically the same ones where germline BRCA1 and BRCA2 mutations predispose to cancer." (PMID 32239503, 2020). "For example, germline mutations in BRCA1 and BRCA2 predispose to multiple cancer types, specifically to ovarian and breast cancer in women and prostate cancer in men." (PMID 32239503, 2020). "Hereditary or sporadic loss of BRCA2 function is associated with various cancers including breast, ovarian, esophageal and prostate cancers." (PMID 31987042, 2020). "For example, ORs for known BC and OC predisposing genes such as BRCA1 and BRCA2 are high, and variants in these genes have been shown to confer high risk to cancer in carriers." (PMID 32726901, 2020). "It has been reported in 90% (breast) and 91% (ovarian) of BRCA1-associated cancers and in 54% (breast) and 84% (ovarian) of BRCA2-associated cancers." (PMID 32481735, 2020). "A 49-year-old unaffected female (BRCA2 PV/LPV carrier) with a strong family history of BRCA1/2-associated cancers lamented that it took almost nine years of “actively searching” before a doctor told her of the availability of genetic testing." (PMID 33110458, 2020). "Genetic testing for germline pathogenic variants in BRCA1 and BRCA2 is widely used in clinical practice to identify individuals at increased risk of breast, ovarian, and other cancers." (PMID 31853058, 2020). "BRCA1 and BRCA2 are the genes most often found mutated and increase the risk for early age onset BC and/or OC, and often after a first cancer a second cancer is common." (PMID 32211400, 2020). "The Alu retroelements are fragments of approximately 300 nucleotides that are reported as being inserted in many genes such as BRCA1 and BRCA2 and are related to an increased cancer risk." (PMID 32039725, 2020). "Our results corroborate these findings, as we observed that the hRAD52 truncation variant is protective against development of cancer in women carrying pathogenic BRCA2 mutations and that this mutation confers a decrease in DSB repair by SSA." (PMID 32175645, 2020). "Across the pan-cancer TCGA cohort, all of the BRCA2 frameshift variants found in LUSC and OV were unique to the African ancestry." (PMID 32471518, 2020). "The identification of the relevant role of BRCA1 and BRCA2 tumor suppressor genes in FA pathogenesis has solidly linked FA genetic background to DNA repair defect, and hence to cancer predisposition." (PMID 32962238, 2020). "Talazoparib has been FDA-approved for its efficacy against cancers with germline BRCA1 or BRCA2 mutations and HER2-negative metastatic breast cancer." (PMID 32046300, 2020).
cancer (continued). "When a germline mutation in BRCA1 or BRCA2 is detected in a cancer patient, genetic testing is indicated in all family members due to the increased risk associated with these mutations." (PMID 32545454, 2020). "As the molecular functions of BRCA1 and BRCA2 have been elucidated, the clinical focus on these cancer predisposition genes shifts toward the development of therapeutic strategies." (PMID 32269964, 2020). "This need for better understanding especially in the context of current combinatorial cancer therapy is highlighted by the fact that BRCA2-deficient tumors under dual PARP inhibition and MUS81 depletion have improved viability compared to either alone." (PMID 33043007, 2020). "Germline mutations in BRCA1 and BRCA2 are associated with an increased risk of developing several types of cancer, including breast, prostate, and ovarian cancer." (PMID 32545454, 2020). "BRCA2-mutation cancers always show a slightly increasing trend of the incidence to be lobular or tubulolobular carcinomas." (PMID 33273622, 2020). "Risk of other cancers such as prostate and pancreatic cancers are also increased in BRCA2 mutation carriers." (PMID 33293522, 2020). "Cancer inactivating BRCA2 mutations are characterized by large tandem duplications and deletions which are typical for RAD52-mediated BIR and SSA repair mechanisms, contributing to rearrangements, fuelling genomic instability and oncogenic transformation." (PMID 31799622, 2020). "Another meta-analysis with 34,911 cases and 48,329 controls showed the genetic relationship between the BRCA2 (BRCA2 DNA repair associated) rs144848 polymorphism and the overall risk of cancer." (PMID 32597485, 2020). "Until then, carriers of mutations in the genes BRCA1 and BRCA2 as well as in other less frequent cancer genes should be taken care of under trial conditions." (PMID 32140806, 2020). "Cancers with BRCA1 or BRCA2 mutations exhibit substantial numbers of rearrangement signature 5 deletions." (PMID 33324554, 2020). "In conjunction, the Supreme Court of the United States overturned Myriad Genetics’ patent on the BRCA1 and BRCA2 genes, which allowed for the development of multi-gene cancer predisposition panels that today are offered by multiple commercial companies." (PMID 31963545, 2020). "Consistent with the previous studies, both BRCA1 and BRCA2 genes contain several cancer risk regions." (PMID 32269964, 2020). "Knowledge levels were high across the cohorts, irrespective of genetic status, education level and time since testing, showing that men retained accurate information about inheritance of BRCA1/BRCA2 mutations and cancer risk." (PMID 29802810, 2019). "Several gene mutations have previously been described to rescue survival of BRCA1-deficient cells, but for BRCA2-deficient cancer cells this remains less clear." (PMID 30626869, 2019). "ATR inhibition further increased the numbers of cGAS‐positive micronuclei and the extent of cytokine production in olaparib‐treated BRCA2‐deficient cancer cells." (PMID 31529615, 2019). "It was previously reported that genetic knockdown of PARG results in sensitization of cancer cells to chemotherapeutic agents and radiation, and tumor-specific killing in BRCA2-deficient cancer cells." (PMID 31827085, 2019). "In agreement with studies from other countries, the combination of MRI and MMG was associated with a diagnosis of cancer at an earlier stage in women with a BRCA1 or BRCA2 mutation undergoing surveillance." (PMID 30980249, 2019). "Our findings reveal that BRCA2-deficient cancer cells show enhanced sensitivity to inactivation of TPX2 or its partner Aurora-A, which points at an actionable dependency of genomically unstable cancers." (PMID 30177840, 2019). "For some women with a BRCA1 and BRCA2 mutation, another strategy to reduce the elevated cancer risk is chemoprevention (e.g. tamoxifen, aromatase inhibitors)." (PMID 31370837, 2019).
cancer (continued). "BRCA2 is a tumor suppressor gene; rare variants in this gene, including rs11571833, are associated with a dramatically increased risk of various cancers including breast, lung, ovarian and prostate." (PMID 31174203, 2019). "The results showed that BRCA1 (P = 0.007) and BRCA2 (P = 0.000129) were selected the genes susceptible to cancer (differentially expressed genes)." (PMID 31865918, 2019). "This condition has been described in diploid BRCA2-associated human cancers and was proposed as a contributor to poor prognosis in patients with diploid BRCA2-associated cancers." (PMID 30930946, 2019). "The BRCA Exchange, part of the BRCA Challenge, is a data-sharing initiative by the Global Alliance for Genomics and Health (GA4GH) and aggregates BRCA1 and BRCA2 data on the impact of genetic variation on cancer risk." (PMID 31013702, 2019). "Women carrying germline mutations in the BRCA1 and BRCA2 genes have a high lifetime risk of developing breast, ovarian, and other cancers." (PMID 30747491, 2019). "Germline mutations of the genes BRCA1 and BRCA2, which encode proteins essential for the repair of double-strand DNA breaks through homologous recombination, lead to increased cancer predisposition." (PMID 30691488, 2019). "Specific agents, such as platinum compounds or poly (ADP-ribose) polymerase (PARP) inhibitors, are effective treatments for some cancers involving BRCA1 or BRCA2 mutation." (PMID 31666926, 2019). "Similar to the results of other studies, we observed an association between germline mutations in BRCA1/BRCA2 and a family history of cancer." (PMID 31244284, 2019). "In comparison, diploid and aneuploid cancers reportedly occur in roughly similar proportions in human BRCA2-associated and non-BRCA2-associated cancers." (PMID 30930946, 2019). "In a recent case-control exome-wide association study of 437 PC cases and 1922 non-cancer controls, only BRCA2 approached significance for enrichment of rare inactivating variants in PC cases." (PMID 31469826, 2019). "By contrast, larger indels (≥3 bp in motif size) were noted to be enriched in cancers with mutations in BRCA1/BRCA2." (PMID 30982602, 2019). "It has been suggested that BRCA2 mutation is associated with increased survival because of the reduced ability of BRCA2 mutated cancer cells to repair damaged DNA caused by chemotherapy." (PMID 31570735, 2019). "Given the role of cancer predisposition factors such as BRCA1/BRCA2 and FA pathway in mitigating R-loops, it is reasonable that persistent R-loops are major contributing factors to cancer-associated genomic instability." (PMID 30813363, 2019). "Germline mutations in BRCA1 and BRCA2 (BRCA)genes confer high risk of developing cancer, especially breast and ovariantumors." (PMID 31067289, 2019). "An important result reported here is that chlorambucil is toxic to cisplatin‐resistant BRCA2‐deficient cancer cells." (PMID 31273933, 2019). "As costs have come down and the benefits of knowing one’s PV status are clear, there have been calls for population-based screening for BRCA1 and BRCA2, as well as other high-risk cancer genes." (PMID 30832243, 2019). "In line with this, a single-nucleotide polymorphism (SNP) near the AURKA gene was previously associated with cancer risk in BRCA2 mutation carriers." (PMID 30177840, 2019). "These outcomes underscore the utility of this model for studying BRCA2-associated genomic aberrations in normal and cancer cells." (PMID 30930946, 2019). "Depletion of TPX2 or its associated kinase Aurora-A preferentially reduced cell viability in a panel of BRCA2-deficient cancer cells." (PMID 30177840, 2019).
cancer (continued). "Reduced recruitment of another DNA exonuclease, MUS81, has also been shown to promote stability of replication forks in BRCA2‐deficient cancers that develop resistance to PARP inhibition." (PMID 30714316, 2019). "Our findings show that BRCA2-deficient cancer cells show enhanced sensitivity to inactivation of TPX2 or its partner Aurora-A." (PMID 30177840, 2019). "In a clinical setting, the identification of BRCA1 or BRCA2 mutations has gained significance as a tool for the implementation of cancer risk-reducing strategies." (PMID 30980249, 2019). "It is often assumed any cancer in a germline BRCA1 or BRCA2 (collectively termed BRCA) mutation carrier was caused by that mutation." (PMID 31360904, 2019). "A number of RAD52 inhibitor leads were reported and showed effects to selectively kill BRCA1- and BRCA2-deficient cancer cells." (PMID 31569559, 2019). "Genomic analyses show the distinct molecular patterning of BRCA1-mutated, HR-deficient cancers compared to BRCA2-mutated amd HR-proficient cancers." (PMID 30683142, 2019). "A paradigm for DNA repair targeted therapy has emerged in cancers that exhibit mutations in BRCA1 or BRCA2 tumor suppressor genes, conferring a strong defect in homologous recombination, a major and error-free DSB repair pathway." (PMID 31921645, 2019). "As with previous studies, there was a higher rate of relevant cancers in BRCA1 variant-positive individuals than in BRCA2, and in women than in men." (PMID 31892343, 2019). "The poly (adenosine diphosphate (ADP)-ribosyl) polymerase inhibitors (PARPi) selectively kill cancer cells with BRCA1 or BRCA2 (BRCA)-mutations." (PMID 31930278, 2019). "High MMP9 mRNA expression levels were associated with the expression of genes involved in cancer progression: BRCA2, COL4A1 and ITGA6, and were also associated with high FABP4 mRNA expression levels." (PMID 31874999, 2019). "BRCA1 and BRCA2 (collectively termed BRCA) are cancer predisposition genes (CPGs) that have been used in clinical practice for over 20 years." (PMID 31360904, 2019). "Mutations of the genes BRCA1 and BRCA2 lead to increased cancer predisposition and are present in approximately 14% of epithelial ovarian cancers, according to recent population-based studies." (PMID 30691488, 2019). "PALB2 is a BRCA2-interacting protein needed for the DNA repair function of BRCA2, and the spectrum of cancers in patients with the biallelic PALB2 mutation is very similar to those with biallelic BRCA2 mutation." (PMID 30840646, 2019). "Carcinomas from patients with TNBC from patients with pathogenic BRCA1/BRCA2 mutations have demonstrated unique sensitivity to platinum agents in both the neoadjuvant and adjuvant settings." (PMID 31379942, 2019). "Five of the seven associations were between cancer phenotypes and gene sets that included BRCA2 which had many PTVs on the genotyping array." (PMID 29691392, 2018). "The close link between BRCA and PARP1 was highlighted in 2005 when two research groups independently discovered that PARP inhibition induces synthetic lethality in mutated BRCA1 or BRCA2 cancers." (PMID 30518089, 2018). "Detection of disease-associated variants in the BRCA1 and BRCA2 (BRCA1/2) genes allows for cancer prevention and early diagnosis in high-risk individuals." (PMID 30646163, 2018). "The discovery of tumor suppressor genes BRCA1 and BRCA2, commonly known as breast cancer susceptibility genes, has been a major milestone in cancer research, diagnostics, and treatment." (PMID 30410429, 2018). "Our work suggests that unforeseen defects in transcription elongation—besides previously reported anomalies in DNA repair, replication, or mitosis—underlie the origins of genome instability and the pathogenesis of cancers in BRCA2 mutation carriers." (PMID 29386125, 2018). "Very promising biomarkers are miRNAs, cancer stem cells, and circulating tumor cells, as well as mutations of the breast cancer 1 gene (BRCA1) and breast cancer 2 gene (BRCA2)." (PMID 30373614, 2018).
cancer (continued). "To date, the scope of BRCA1 and BRCA2 testing has been substantially larger than any other cancer predisposition gene, yet the ability to look across the spectrum of publicly available data has not been coordinated." (PMID 30586411, 2018). "Germline mutations in either BRCA1 or BRCA2 are associated with increased predisposition to breast, ovarian and other cancers." (PMID 29545922, 2018). "We identified 25 PSSs in BRCA2, where some positions mapped close to natural variants associated with cancer." (PMID 30487452, 2018). "Cancer-associated BRCA2 mutations diminish PAF1 recruitment to the polymerase, provoking unscheduled R-loop accumulation at promoter-proximal pause sites and triggering DNA breakage." (PMID 29386125, 2018). "We evaluated MutationTaster, Polyphen2, SIFT, PROVEAN algorithms, analyzed segregation with cancer disease (in both families with identified BRCA2 variants) and in one family performed LOH (based on 2 primary tumors)." (PMID 30286154, 2018). "Notable exceptions are the BRCA1 and the BRCA2 genes, whose mutations have high penetrance and are found in nearly 40% of cancer patients." (PMID 30263092, 2018). "Nevertheless, the variant segregated with BRCA2-related cancer disease in the family and in silico prediction algorithms indicated it affected BRCA2 protein function." (PMID 30286154, 2018). "BRCA2 inactivation by depletion or cancer-causing mutations instigates RNAPII accumulation and R-loop accrual at PPP sites in actively transcribed genes, accompanied by γH2AX formation marking DNA breakage, which is reduced by ERCC4 endonuclease depletion." (PMID 29386125, 2018). "At least one of the Neanderthal variants (position) is likely pathogenic, as the BRCA2 SNP has been recorded by COSMIC database in association with two cancer types, haemangioblastoma and rhabdomyosarcoma." (PMID 30410429, 2018). "Although PARP inhibitors are now exploited clinically to treat BRCA1- and BRCA2-mutated cancers, the nature of the DNA structures on which PARP enzymes are “trapped” by these inhibitors is unclear." (PMID 29983321, 2018). "The level of cancer risk associated to PALB2 pathogenic variants is known to be low in comparison to BRCA2 pathogenic variants, but enough to propose a clinical management of the familly contrary to other low risk genes, notably CHEK2 1100delC and ATM." (PMID 29707112, 2018). "Taken together, our findings demonstrate that RNAPII and BRCA2 interact in human cells and that the cancer-associated BRCA29000insA truncated mutant protein retains this interaction." (PMID 29386125, 2018). "This argument appears even stronger for BRCA2 mutation carriers whose cancers often remain in situ for several years." (PMID 30513626, 2018). "Both BRCA1 and BRCA2 are oncosuppressor genes involved in DNA repair and are commonly mutated in a number of cancers." (PMID 29346284, 2018). "The identification of BRCA1 and BRCA2 germline mutations as predictors of cancer susceptibility significantly improved the diagnosis and prevention of hereditary breast and ovarian cancers (HBOC)." (PMID 29338689, 2018). "Global protocols and standards differ widely when it comes to analyzing variants in the BRCA1 and BRCA2 cancer susceptibility genes." (PMID 29479477, 2018). "By contrast, patients carrying BRCA2 mutations (all but one being ER-positive) had a significantly higher response rate than sporadic cancer." (PMID 30544963, 2018). "Germline mutations were identified in three cases: 2/48 cases with breast (4.2%) and 1/19 cases with ovarian (5.3%) cancer carried pathogenic deleterious germline mutations in the BRCA2 gene." (PMID 29464067, 2018). "Loss of heterozygosity (LOH) precedes cancer development such that only the tumor is null for BRCA2." (PMID 31435521, 2018).